BRAF (B-Raf proto-oncogene, serine/threonine kinase)
Diseases named in the same sentence as BRAF in open-access papers (continued):
Sharing a sentence is not in itself a finding about the gene and the disease.
colorectal cancer (continued). "The suboptimal MAPK signaling with dabrafenib plus trametinib in colorectal cancer may be explained by an epigenetic mechanism including the utilization of epidermal growth factor receptor signaling to maintain BRAF-MEK-ERK signaling in the face of BRAF inhibition." (PMID 37059834, 2023). "Because these inhibitor pairs did not suppress cancer cell stemness, we aimed to study the effectiveness of a triple drug combination against BRAF, MEK, and EGFR that was used in a clinical trial for patients with BRAFmut colorectal cancer." (PMID 37791907, 2023). "BRAF and KRAS are two key oncogenes that determine response to anti-EGFR therapies in colorectal cancer patients." (PMID 37483495, 2023). "To test its potency against KRAS and BRAF mutant colorectal cancer cells, we treated three KRAS-mutant cancer cell lines (HCT116, LS513, and SW620) or a BRAF-mutant cancer cell line (HT29) with SJ-C1044 in a cell growth assay." (PMID 37504287, 2023). "evaluate deep-learning-based prediction for MSI, BRAF, KRAS, NRAS, and PIK3CA biomarker status in colorectal cancer from histopathology slides." (PMID 36958327, 2023). "However, the straight relationship between MLH1 hypermethylation and BRAF p.V600E mutation might be called into question by the fact that not all colorectal cancers with BRAF p.V600E mutations display silenced MLH1 with subsequent MSI." (PMID 37190216, 2023). "EGFR pathway is an adaptive mechanism of resistance in colorectal cancer and that concurrent EGFR pathway inhibition is needed in the treatment of BRAF V600-mutant colorectal cancer." (PMID 36801912, 2023). "The highest OR estimate was found for BRAF‐mutated colorectal cancer, n = 1086 (ORfully adj: 1.67, 95% confidence intervals [CI]: 1.36‐2.05), with an attenuated association observed between diabetes and colorectal cancer without BRAF‐mutations, n = 7959 (ORfully adj: 1.33, 95% CI: 1.19‐1.48)." (PMID 35383926, 2022). "In the future, as research on colorectal cancer progresses, many new prognosis-related variables, including microsatellite status (MSS), RAS, and BRAF genes, will be gradually discovered." (PMID 36048198, 2022). "BRAF mutant patients and even more so BRAF/PIK3CA double mutant colorectal cancers in TCGA tended to be of earlier stage (stages I and II) than BRAF wild type disease (p = 0.003)." (PMID 36079062, 2022). "NTRK gene fusions are prevalent in BRAF wild‐type, MLH1 promoter hypermethylated non‐Lynch syndrome, microsatellite instability‐high colorectal cancer patients." (PMID 36127731, 2022). "However, the number of BRAF‐mutated tumors in the rectum was much lower than in the colon, which may explain why the observed difference in the association between diabetes and colorectal cancer risk by BRAF‐mutation status was not statistically significant." (PMID 35383926, 2022). "We aimed to investigate the frequency and clinicopathological characteristics of double-mutant colorectal carcinoma and its differences from KRAS/BRAF single-mutant colorectal carcinoma using bioinformatics tools." (PMID 35280113, 2022). "Colorectal cancer patients need to undergo KRAS, NRAS, BRAF, HER2 and microsatellite instability analysis." (PMID 34681592, 2021). "BRAF is a downstream effector of KRAS, and its prognostic value in colorectal cancer is widely accepted." (PMID 34884530, 2021). "For colorectal cancer module, the analysis revealed the occurrence of approved drug targets TYMS, TOP1, BRAF and EGFR." (PMID 35053185, 2021). "Detection of some genes such as c-MYC, KRAS, BRAF, PIK3CA, PTEN can be used as a predictor of colorectal cancer." (PMID 33014884, 2020).
colorectal cancer (continued). "Other studies using colorectal cancer (CRC) cell lines and a mouse xenograft model revealed that, in the presence of BRAF V600E, the expression of growth regulation by estrogen in breast cancer protein 1 (GREB1) is highly upregulated compared to WT." (PMID 33198372, 2020). "In addition, patients that regularly use NSAIDs may reduce their risk of certain subtypes (i.e., those with no BRAF/KRAS gene mutation) of colorectal cancer (CRC)." (PMID 32722165, 2020). "Analysis of KRAS, BRAF and PI3KCA genes helps in the prognosis as well as in the treatment of colorectal cancer." (PMID 32000721, 2020). "Colorectal cancer (CRC) is a heterogeneous disease with a complex biology and a wide number of altered genes such as BRAF, KRAS and PIK3CA." (PMID 32066410, 2020). "Since then, in 2015, all patients having a resection for a diagnosis of colorectal cancer in the North East of Scotland have had the KRAS, BRAF and MSI status assessed on their surgical specimen." (PMID 32041565, 2020). "Sidedness is a surrogate of a wide spectrum of colorectal cancer (CRC) biology features (embryology, microbiome, methylation, microsatellite instability (MSI), BRAF, aging, KRAS, consensus molecular subtypes (CMS), etc.), which result in prognostic factors." (PMID 32545884, 2020). "This study aimed to characterize the ATP-synthesis by oxidative phosphorylation in colorectal cancer (CRC) and premalignant colon polyps in relation to molecular biomarkers KRAS and BRAF." (PMID 32231083, 2020). "In advanced clinical practice, the oncological management of colorectal cancer requires prior knowledge of KRAS, NRAS, and BRAF status, for the design of appropriate therapeutic strategies, with more gene mutations still surfacing as potential biomarkers." (PMID 31623125, 2019). "Molecular assessment of colorectal cancer (CRC) is receiving growing attention, beyond RAS and BRAF, because of its influence on prognosis and prediction in cancer treatment." (PMID 31717544, 2019). "Our experiments highlight key differences between oncogenic BRAF and KRAS in colorectal cancer and find unexpected heterogeneity in a signalling pathway with fundamental relevance for cancer therapy." (PMID 31266962, 2019). "Only three biomarker-drug-tumour combinations had both types of responses: the triplets ‘BRAF V600E-panitumumab, trametinib-colorectal cancer’, ‘EGFR R451C-cetuximab-colorectal cancer’ and ‘KRAS G13D-cetuximab-colorectal cancer’." (PMID 31169290, 2019). "We present the case of a 67 year old Caucasian male that was initially treated with BRAF inhibitors followed by anti-CTLA4 and then anti-PD1 immunotherapy for metastatic melanoma but later developed colorectal cancer." (PMID 31727009, 2019). "In colorectal cancers, tumour‐specific gene alterations of EGFR, BRAF, ALK, KIT, PDGFR, HER2 and KRAS75, 76, 77 were detected via ctDNA‐based assays." (PMID 30873683, 2019). "In colorectal cancer, the genes that were significantly enriched for copy number gain in TCGA versus GENIE were BRCA2 (60% versus 23%, p < 0.0001), BRAF (48% versus 11%, p < 0.0001) and KRAS (22% versus 3%, p < 0.0001)." (PMID 30728399, 2019). "Over 24 months, 264 specimens from colorectal cancer (CRC) patients were brought to our laboratory for KRAS, NRAS, and BRAF characterization." (PMID 31036005, 2019). "PN-1 was reported to be up-regulated by oncogenic activation of Ras, BRAF and MEK and contributes to pro-neoplastic actions of ERK signaling in colorectal cancer cells." (PMID 31501409, 2019).
colorectal cancer (continued). "Hsa-miR-375 also seems to affect colorectal cancer cell sensitivity to cetuximab by targeting PHLPP1 and BRAF." (PMID 29930763, 2018). "Since the discovery that BRAF and KRAS are oncogenic drivers of colorectal cancer, much progress has been made in understanding their common and individual effects." (PMID 29907857, 2018). "The BRAF inhibitor AZ304 has broad spectrum antitumour activity, which is significantly enhanced by combination with Cetuximab in colorectal cancers in vitro and in vivo." (PMID 29755114, 2018). "Accordingly, combined BRAF and EGFR inhibition showed synergistic efficiency in colorectal cancer cells in vitro and in vivo." (PMID 29192388, 2018). "The aim of this study was to validate a molecular classification of colorectal cancer (CRC) based on microsatellite instability (MSI), CpG island methylator phenotype (CIMP) status, BRAF, and KRAS and investigate each subtype’s response to chemotherapy." (PMID 30188916, 2018). "In the metastatic setting for colorectal cancer, FOLFOXIRI plus panitumumab or bevacizumab has shown promising clinical activity in Ras–BRAF wild-type patients." (PMID 30263096, 2018). "We used the BRAF and KRAS wildtype CaCO2 colorectal carcinoma cell line, harboring Doxycycline inducible constructs expressing BRAFV600E and KRASG12V as well as cell lines with naturally occurring BRAFV600E (HT29) and KRASG12V (SW480) mutations." (PMID 29907857, 2018). "The results from this work suggest that the majority of colorectal cancers are largely homogenous in terms of KRAS, BRAF and CIMP status." (PMID 28097409, 2017). "A key observation is that the vast majority of colorectal cancer expresses EGFR and the inhibition of BRAF triggers the activation of EGFR." (PMID 29312543, 2017). "The aim of the study was to evaluate the current rate of molecular testing prescription (KRAS codons 12/13, BRAF and microsatellite instability (MSI)) in newly diagnosed colorectal cancer (CRC) patients and to determine which factors influence testing." (PMID 29137623, 2017). "Here, the authors present BaseScope, a mutation-specific RNA in situ hybridization assay and spatially map colorectal cancer and adenoma KRAS, BRAF and PIK3CA driver gene mutant subclones." (PMID 29222441, 2017). "About 40% colorectal cancers (CRCs) contain KRAS or BRAF mutant genes and are resistant to treatments with individual inhibitors of RTKs, AKT, MEK, or BRAF." (PMID 28002807, 2017). "We initially examined the effect of BRAF/MEK and PI3K/MTOR pathway inhibitors on cell signaling and autophagy of BRAFV600E bearing colorectal cancer cell lines, in order to have a first indication on the potential regulation of autophagy by these two pathways." (PMID 26802026, 2016). "We used two kinds of BRAF specific compounds, PLX4032 and PLX4720, in colorectal cancer HT29 cells in culture, and measured whole metabolites by CE-MS analysis." (PMID 27924922, 2016). "As with lung cancer, the most well-described driver alterations in colorectal cancer (for example, ‘hotspot alterations’ in KRAS, BRAF, NRAS and PIK3CA) are concordant between primary tumors and metastatic lesions." (PMID 25808843, 2015). "The panel allows the detection of mutations that are currently considered as actionable (NRAS, KRAS) or putatively actionable (BRAF, PIK3CA) in colorectal cancer." (PMID 26047774, 2015). "BRAF is also important in the development of colorectal carcinoma (CRC)." (PMID 25784606, 2015). "In addition, given that non-KRAS-mutated tumors include a distinct subset characterized by BRAF mutation, analyses were also performed to compare KRAS-mutated tumors with both BRAF-mutated tumors and the remaining subset of colorectal carcinomas, with observed neither somatic oncogene mutation." (PMID 25929517, 2015). "Based on these discoveries, clinical trials are underway testing combined inhibition of BRAF and EGFR in colorectal cancer (NCT01750918)." (PMID 25520658, 2014).
colorectal cancer (continued). "Moreover, the significantly lower incidence of BRAF mutations in our study suggests the existence of a possibly higher number of familial syndromes like HNPCC that are characterized by a virtual lack of BRAF abnormalities in colorectal cancers." (PMID 25005754, 2014). "We evaluated the outcome of 68 patients with advanced colorectal cancer and RAS, BRAF and PI3KCA status according to ALK gene status (disomic vs. gain of ALK gene copy number – defined as mean of 3 to 5 fusion signals in ≥10% of cells)." (PMID 24691006, 2014). "Numerous signaling cascades including KRAS/BRAF and PI3K/AKT were certified to entangle in colorectal cancer." (PMID 23825635, 2013). "In BRAF V600E mutant colorectal cancer cells the amplification of the BRAF gene was identified as mechanism of resistance to MEK and BRAF inhibition." (PMID 24298448, 2013). "Given the lack of association with the BRAF V600E mutation, as well as the fact that Lynch syndrome colorectal carcinomas arise from conventional adenomas, the association between exon 20 mutations and MSI-high might not be related to the serrated neoplasia pathway as has been previously suggested." (PMID 23785428, 2013). "In the LARC population studied here, the observed frequencies of tumor aberrations of KRAS, BRAF, PIK3CA, and ERBB2 were in the order of magnitude previously reported in colorectal cancer." (PMID 23226389, 2012). "The potential predictive and prognostic biomarkers which have stemmed from the study of the genetic basis of colorectal cancer and therapeutics are discussed with a focus on mismatch repair status, KRAS, BRAF, 18qLOH, CIMP and TGF-β." (PMID 24212777, 2011). "Most cancers with atypical KRAS mutations (291/335, 86.9%) had no additional mutations in BRAF, NRAS, or NF1, with the incidence of these mutations being far lower than the incidence of concomitant Ras mutations in atypical BRAF colorectal cancers." (PMID 39751654, 2025). "The protein kinase B-Raf proto-oncogene (BRAF), situated downstream of RAS within the RAS-RAF-MEK-ERK kinase cascade, assumes a pivotal role in cellular signal transduction, manifests itself in approximately 8%–10% of patients diagnosed with colorectal cancer." (PMID 40271196, 2025). "Of 335 colorectal cancers harboring atypical KRAS mutations in the combined cohorts, 317 (94.6%) had no concomitant pathogenic BRAF mutation, with BRAF mutations in the remaining 18 all belonging to class 3 (18/335, 5.4%)." (PMID 39751654, 2025). "Indeed, we observed that in colorectal cancer cell lines HCT15 (RAS-mutant) and RKO (BRAF-mutant), MEK and RAC inhibitors exhibit a synergistic suppressive activity." (PMID 41465386, 2025). "As it is essential to consider ITH during preclinical development of anticancer therapeutics, we chose a panel of colorectal cancer PDOs spanning genetic (e.g., MSI/MSS and KRAS/BRAF /APC status), clinical stage, anatomic location, chemosensitivity, and CSC composition." (PMID 40882026, 2025). "In a pan-cancer BRAF basket study, vemurafenib showed marked activity in BRAF-mutant lung and other tumors but not in colorectal cancer, revealing lineage-dependent signaling differences." (PMID 41463612, 2025). "In the context of colorectal cancer, this mechanism provides an alternative pathway for driving tumorigenesis in cases lacking canonical KRAS, NRAS, or BRAF mutations." (PMID 40868090, 2025). "Of the 335 colorectal cancers, 13 (3.88%) with atypical KRAS also carried a typical KRAS mutation, and none of those tumors had an additional BRAF, NRAS, or NF1 mutation." (PMID 39751654, 2025). "Colorectal cancers with V600E BRAF mutations may be treated with combinations of small molecule BRAF inhibitors and anti-EGFR monoclonal antibodies and the less common HER2 over-expressing colorectal cancers may be treated with drugs targeting this alteration." (PMID 40061138, 2025).
colorectal cancer (continued). "In colorectal cancer, KRAS, NRAS, BRAF, and PIK3CA mutations induce a negative effect on the response to anti-EGFR therapies." (PMID 38248103, 2024). "However, very limited response to this same drug was observed in colorectal cancer studies that revealed that BRAFV600E tumor cells presented a rapid feedback activation of EGFR expression that mediated resistance to BRAF inhibitors." (PMID 39018564, 2024). "It is indicated in patients whose tumors have progressed following prior treatment or have no other alternative treatment options except those with colorectal cancer due to resistance to BRAF inhibition." (PMID 39518080, 2024). "The meta-analysis supports the use of EGFR mAbs in the treatment of mCRC without mutations in KRAS, particularly for left-sided colorectal cancer and where the tumour does not harbour NRAS or BRAF mutations." (PMID 38402342, 2024). "Although this study did not validate the ctDNA assessment methods and lacked standard positive controls, data obtained using positive and negative control samples from BRAF-positive colorectal cancer showed 100% concordance." (PMID 39336882, 2024). "While the guidelines on colorectal carcinoma management recommend KRAS and BRAF V600E mutation analysis, this is not routinely performed in our country." (PMID 39364024, 2024). "As an E3 ubiquitin ligase, only two experimentally validated substrates of RNF149 were reported so far: wild-type but not mutant BRAF in colorectal cancer, and EPHA2 in NPC." (PMID 37958377, 2023). "Previous studies have shown that simultaneous BRAF gene and NRAS gene mutations are virtually absent in individual colorectal cancer patients." (PMID 37037831, 2023). "Since dual BRAF and ERK1/2 inhibition effectively abrogates clonal outgrowth of BRAFV600E colorectal cancer cells, which have relatively high intrinsic resistance to BRAFi/MEKi combination, the addition of ERK inhibition to the combination strategy is promising." (PMID 37834284, 2023). "Although substantial advances have been made in the treatment of genetically defined subtypes, such as RAS/BRAF wild-type and BRAFMT colorectal cancer, an effective therapeutic strategy for KRASMT colorectal cancer, the most common genetically defined subtype (∼40%–45%) is still lacking." (PMID 36279564, 2023). "Whether BRAF inhibitors and/or immunotherapy will be more broadly successful in patients with EP-PD-NEC, as seen in colorectal cancer, awaits further large prospective clinical trials." (PMID 37894318, 2023). "In colorectal cancer, reduced FABP1 expression was linked to poor-grade, right-sided tumor location, microsatellite instability (p < 0.0001 each), and absence of BRAF V600E mutations (p = 0.001), but unrelated to pT and pN status." (PMID 35951102, 2022). "While combination inhibition with alpelisib, cetuximab, encorafenib, and binimetinib has been trialed in B-Raf proto-oncogene, serine/threonine kinase (BRAF)-mutant colorectal cancer, evidence for ER+ breast cancer is lacking." (PMID 36046843, 2022). "AZ304, a potent dual BRAF inhibitor of both wild-type and BRAF-V600E mutant BRAF, exerts anti-tumor effects in colorectal cancer independent of BRAF genetic status." (PMID 36585710, 2022). "Further evaluation of the recommended molecular biomarkers for colorectal cancers, including more number of codon of KRAS, NRAS and BRAF, may also be required." (PMID 36083889, 2022).